PLK1 (polo like kinase 1)
Diseases named in the same sentence as PLK1 in open-access papers (continued):
Sharing a sentence is not in itself a finding about the gene and the disease.
cancer (continued). "Next, we examined the therapeutic potential of targeting the cell cycle regulator PLK1 that was identified both by differential expression analysis and multivariate partial-least squares regression as a predictor of poor lapatinib response in fibroblast-protected cancer cells." (PMID 39513002, 2024). "Intriguingly, cancer cells treated with inhibitors of the mitotic kinase Plk1 or the chemotherapeutic drugs abiraterone or Taxol also underwent entosis due to mitotic disruption, suggesting that this mechanism could have clinical significance in cancer therapy." (PMID 38565900, 2024). "Therefore, PLK1 is regarded as a promising target for cancer therapy." (PMID 38495493, 2024). "The identification of cell cycle associated with many DEGs, including PLK1, ANLN and KIF18B/20A, across human cancers demonstrates that the most essential characteristic of cancer cells is sustained proliferation, and that this may lead to adverse survival outcomes." (PMID 38096046, 2024). "Additionally, PLK1 is indispensable for re-entering mitosis following recovery from G2 phase arrest induced by DNA damage, justifying its exploration as a potential therapeutic target for cancer." (PMID 38255993, 2024). "Thus, PLK1 is widely regarded as a potent proto-oncogene and a promising target for cancer therapy." (PMID 37958623, 2023). "Thus, PLK1 inhibitors are considered potential antimitotic agents for cancer treatment." (PMID 36611980, 2023). "This suggests that UBE2C and PLK1 may play important roles in the development of pan-cancer." (PMID 37958642, 2023). "This can be used to target cancers with overexpression of oncogenes, for example, mitotic arrest deficiency 2 (MAD2) and protein-coding phosphatase 2 (PP2A), cyclin-dependent kinase regulatory subunit 1B (CKS1B) and Polo-like kinase 1 (PLK1), KRAS and CDKN1A (p21)." (PMID 37896193, 2023). "Therefore, phosphorylation of β-catenin at Ser-311 by PLK1 promotes cancer metastasis in vivo." (PMID 36793862, 2023). "Indeed, it has been reported that tetraploid cancer cells are hypersensitive to PLK1 inhibition." (PMID 37639469, 2023). "Considering the growing list of synthetic lethal gene pairs with ARID1A deficiency, it may be interesting to investigate the efficacy of combinational therapy of PLK1 inhibitor and agents targeting synthetic lethal phenotypes in ARID1A-mutated cancers, such as PARP inhibitors and ATR inhibitors." (PMID 36980292, 2023). "However, PLK1 has been determined to be a broad-spectrum anti-cancer target." (PMID 36676076, 2023). "KIF18A is a druggable enzyme that may synergize with PLK1 inhibition in cancer treatments." (PMID 37639469, 2023). "In addition, an evaluation of disease-free survival in 26 cancer types demonstrated a negative association with PLK1 expression in 7 cancer types." (PMID 37174744, 2023). "Thus, it has been proposed that the expression of PLK-1 could be used as a therapeutic target for various types of cancers." (PMID 37570823, 2023). "If site-specific PLK1 demethylation can be performed in the future, applying replication stress only to mitotic cancer cells may be possible, and in combination with radiotherapy, achieving tumor-specific radiosensitization with less toxicity to healthy tissues may be possible." (PMID 35773310, 2022). "Therefore, HN1L promoted cancer progression by up-regulating the expression of PLK1." (PMID 36476988, 2022). "Thus, in addition to direct toxicity in cancer cells, inhibiting PLK1 may enhance anti-tumor immunity and synergize with immunotherapy." (PMID 35871223, 2022).
cancer (continued). "In this work, we uncover that SETD3 likely regulates PLK1 levels directly, which might provide a combinational way through simultaneous inhibition of PLK1 activity and reduction of PLK1 transcriptional levels to deal with drug resistance of cancer cells." (PMID 35912180, 2022). "However, PLK1 misregulation has been described in different tumor types, contributing to tumor development and progression, and it is reported to be overexpressed in many cancers compared to the normal tissue." (PMID 36142803, 2022). "Therefore, the utility of PLK2 as a biomarker may have a broader application and provide a therapeutic window for the use of PLK1 inhibitors in multiple types of cancers." (PMID 35156101, 2021). "Hence, we considered Plk1 as an interesting target in these cancers." (PMID 34646387, 2021). "Due to poor cancer cell selectivity of microtubule-targeting drugs and their side effects, such as peripheral neuropathy, new anti-mitotic compounds have been actively developed against e.g., mitotic motor proteins Eg5 and Cenp-E, Plk1 and Aurora kinases, and other key facilitators of cell division." (PMID 34926718, 2021). "Although it is unclear whether PLK1 directly phosphorylates β-actin in Ser33, the crucial role of this kinase in cancer cell division suggests that PLK1-dependent actin phosphorylation may control actin function (by controlling actin polymerization and/or cross-linking) in cancer cell proliferation." (PMID 36046434, 2021). "Given that loss of APC/CCdh1 activity is associated with genomic instability and tumorigenesis it is tempting to speculate that upregulation of Claspin, Chk1, Cyclin A, and Plk1 may contribute to genomic instability and cancer, in part, via antagonism of APC/CCdh1." (PMID 32345958, 2020). "In the present study we investigated, for the first time, if novel siRNNs could enter primary peripheral blood and bone marrow mononuclear cells from pediatric B-ALL patients and induce knockdown of Plk1 mRNA, a key player in the cell cycle and a promising target in cancer therapy." (PMID 32060361, 2020). "Polo-like kinase 1 (Plk1), belonging to the enzyme family of polo-like kinases, is a multifunctional regulator of cell-cycle progression, which has been widely shown to be overexpressed in a multitude of cancer entities including OC and to correlate with poor patient prognosis." (PMID 33117692, 2020). "Therefore, we suggest USP7 is a promising target for cancer therapy, and combination therapy with inhibitors of PLK1 and USP7 may be valuable for treating paclitaxel-resistant cancers, because of their strong synergism." (PMID 33207738, 2020). "Thus, Plk1 inhibitors may have potential for applications in combined treatment with α/β-tubulin and γ-tubulin inhibitors for cancer chemotherapy." (PMID 33584305, 2020). "Importantly, previous studies have identified that PLK1 is highly expressed in a variety of cancers including HCC, pancreatic carcinoma and renal cell carcinoma, and it is associated with decreased survival in cancer patients." (PMID 32463161, 2020). "We also evaluated whether the active form of PLK1 triggers the tumorigenicity of cancer." (PMID 31548612, 2020). "Therefore, PLK1 was considered a promising target for anti-cancer drug development." (PMID 32231733, 2020). "However, detailed mechanisms of the actions of PLK1 inhibitors on KRAS mutant cancers are largely unknown." (PMID 32486290, 2020). "The discovery of genistein being a Plk1 inhibitor adds a new horizon for the possible application of genistein as adjuvant in chemotherapy because of its ability to prevent cancer cells from acquiring resistance against the anticancer drugs or due to resensitize drug-resistant cancer cells." (PMID 31866857, 2019).
cancer (continued). "Therefore, PLK1 functions by complex mechanisms to regulate DNA replication after stress as well as mitosis, in ways that may be relevant to responses to cancer treatment and tumor development, including in RMS." (PMID 31824851, 2019). "Thus, it is possible that cancer therapy based on Plk1 inhibition could increase genomic instability in cells that survive it." (PMID 30875364, 2019). "Understanding the role of CDK1 and PLK1 in the maintenance of centrosomes and primary cilia and in postmitotic differentiation programs is important not only for basic research but also for clinical practice because both these kinases are considered as attractive targets for cancer therapy." (PMID 31295970, 2019). "Additionally, as a potential small molecular inhibitor of PLK-1, DHM may prevent cancer progression by inhibiting PLK-1 enzymes." (PMID 31770410, 2019). "Besides, PLK1 inhibitors may induce a cell cycle arrest at the G2-M phase and apoptosis in cancer cells." (PMID 31387297, 2019). "Likewise, Plk1 inhibitors lead to diverse biological effects in cancer cells." (PMID 31040125, 2019). "Thus, we propose that the Cdk/Pin1/Plk1 axis is a common feature of the activation of mitotic transcription factors, which may also be helpful to identify cancers with poor survival prognosis." (PMID 30321399, 2019). "In addition to the negative regulation of TCR signaling, knockout of WAS could also activate PLK1 signaling, which has been suggested to serve as oncogenic signaling in most human cancers." (PMID 30619485, 2018). "Hence, the inhibition of PLK1 has been suggested as a potential strategy for cancer therapy." (PMID 30631355, 2018). "In addition, EGC, as another kind of catechins, also could lead cell-cycle arrest in S and G2/M phases by disturbing the proper cellular localization of PLK1, finally inducing apoptosis in several cancer cells including HeLa cells." (PMID 30213130, 2018). "Thus, many PLK1 inhibitors have been developed as potential cancer therapeutic agents." (PMID 29765534, 2018). "Hence, the PLK1 inhibition and immunotherapy combination could be promising in cancer treatment, although it needs to be proved by further experimental and clinical validations." (PMID 30631355, 2018). "Characterization of centrosome abnormalities in various cancer cell lines has revealed that supernumerary centrosomes, when devoid of centrioles, were unable to nucleate microtubules despite the presence of sufficient gamma-tubulin, pericentrin, PLK1 and AURKA proteins." (PMID 29370237, 2018). "Thus, an improved understanding of DNA-related metabolism involving PLK1 will be met with keen interest, as such information could facilitate the effective use of PLK1 inhibitors during cancer therapies." (PMID 29254517, 2017). "Therefore, PLK1 has been investigated as a target for cancer therapy." (PMID 29186071, 2017). "Importantly, several studies have shown that inhibiting PLK1 expression or function by antibodies, RNAi, or small molecule inhibitors leads to mitotic arrest and apoptotic cell death in a wide range of human cancer cells, and is sufficient to prompt tumor regression in mouse xenograft models." (PMID 28953239, 2017). "We thus envision that inhibiting Plk1 in combination with other chemicals that target metabolism and macromolecular biosynthesis in cancer cells could potentially provide unique rationale for cancer therapy." (PMID 29138396, 2017). "As a consequence, PLK1 might act as a cancer promoting factor and participate in GC tumorigenesis." (PMID 29190933, 2017). "Hence, Plk1 is believed to be an attractive therapeutic target for cancer cells." (PMID 27902479, 2017).
cancer (continued). "Similarly PLK1, which is well known to control metaphase to anaphase transition and mitotic exit, is upregulated in these cancers and pre-clinical as well as clinical data collectively suggest that PLK1 inhibition can be a promising strategy in cancer therapy." (PMID 29212506, 2017). "Hence, strategies of inhibiting PLK-1 may be utilized for sensitizing the resistant cancer cells to targeted drug therapies." (PMID 28415805, 2017). "Thus, targeting Plk1 may permit the induction of cancer-cell-selective mitotic block and apoptotic cell death in Plk1-addicted cancers." (PMID 28721210, 2017). "Thus, it has been repeatedly proposed that PLK1 could be a particularly attractive target for anti-cancer drug discovery." (PMID 28953239, 2017). "Importantly, our screening strategy also identified previously undescribed drug interaction patterns and several novel combinations with high efficacy against KRAS-mutant cancers, for example, the combined inhibition of PLK1 and ROCK (CI=0.33 at median effective dose)." (PMID 27193833, 2016). "Furthermore, our novel findings may be generalizable to many other cancers since preliminary clinical evidence suggests that PLK1 is involved in the development of several other human cancers." (PMID 27003818, 2016). "Several reports had documented that inhibition of PLK1 in variety cancer cell lines could result in growth reduction and induce apoptosis; however, the detailed mechanism of how PLK1 interaction with the cellular apoptosis pathway is still known and needs further investigation." (PMID 26090465, 2015). "These fundamental differences in the biochemical properties of the KD versus the PBD predict that ATP analog inhibitors would annihilate Plk1 catalytic activity in both normal and cancer cells equally, whereas PBD inhibitors could interfere with only a subset of PBD-dependent interactions." (PMID 26500787, 2015). "Interfering with Plk1 activity and/or expression using dominant-negative mutants, antibody microinjection, antisense oligonucleotides, small interfering RNAs or kinase inhibitors leads to different mistakes in centrosomal maturation, mitotic catastrophe and increased apoptosis in cancer cells." (PMID 26317649, 2015). "Thus, it suggested that the cell invasion is independent of the cell cycle; this may give us a possible explanation why inhibition of PLK1 only partial reduced the invasion capability of cancer cell." (PMID 26090465, 2015). "In this review, we discuss the biologic rationale for Plk1 inhibitors in cancer, the clinical development of volasertib to date in solid tumors and AML, and the future identification of biomarkers that might predict response to volasertib and help determine the role of this agent in the clinic." (PMID 25027517, 2015). "Therefore, we presume that PLK1 expression can be the important marker for HCC diagnosis; moreover, PLK1 may be the target for cancer treatment." (PMID 25019081, 2014). "Interfering with Plk1 activity and/or expression with dominant-negative mutants, antibody microinjection, antisense oligonucleotides or small interfering RNAs leads to different mistakes in centrosomal maturation, mitotic catastrophe, increased apoptosis and tumor inhibition in cancer cells." (PMID 24810255, 2014).
cancer (continued). "The PLK1 inhibitor I2, and its analogs, may have potential in cancer therapeutics." (PMID 23658603, 2013). "Overexpression of Plk1 could be also a prognostic marker for many cancers." (PMID 24216699, 2013). "Although chemical inhibitors of PLK1 are being developed for clinical use, the long expensive process of drug development prompts the question of whether currently approved off-patent drugs may have undiscovered anti-cancer potential." (PMID 23047041, 2012). "Beta-carboline derivatives show significant antitumor activity, and we previously demonstrated that a beta-carboline derivative DH166 inhibits the kinase activity of PLK1 in vitro, suggesting that this group of compounds may inhibit the growth of cancer cells by targeting PLK1." (PMID 23056340, 2012). "Previous data suggest that beta-carboline derivatives might inhibit the growth of cancer cells through multiple targets such as DNA topoisomerase and cyclin-dependent kinase, but our data indicate that PLK1 is likely the key target based on the following observations." (PMID 23056340, 2012). "For example, high levels of Plk1 are indicative of a poor prognosis in esophageal, non-small cell lung cancer and oropharyngeal carcinomas and have been observed in various forms of cancers including gastric, breast, ovarian, endometrial, gliomas, thyroid and melanomas." (PMID 21324136, 2011). "Collectively, PLK-1 could be an excellent target for cancer therapy." (PMID 21884621, 2011). "However, recent findings suggest that PLK1 activity is frequently mis-regulated in human cancers." (PMID 20711360, 2010). "Therefore, Plk1 is proposed as a prognostic marker for human cancers." (PMID 19161615, 2009). "However, it should be pointed out that cancer cells might behave differently and thus the role of Plk1 overexpression in aneuploidy deserve further consideration." (PMID 20003272, 2009). "Polo-like kinase 1 (PLK1), an essential regulator of mitosis, is known to stabilize β-catenin in various cancers." (PMID 41608586, 2026). "Deubiquitinase USP38 binds to PLK1 to stabilize PLK1 expression, facilitating DDR in OC cells and enhancing cancer cell proliferation, thereby reducing the apoptosis rate of cancer cells." (PMID 41854204, 2026). "IHC analysis confirmed cancer-specific enrichment of strong HSP60 positivity compared to benign tissues, a pattern absents for CDK1 and PLK1." (PMID 41522350, 2026). "Mechanically, silencing USP38 decreased the expression level of PLK1 protein, repressing DDR in cancer cells." (PMID 41854204, 2026). "The authors reported that MSNPs inhibit cancer cell invasion via ROS- and NOX4-dependent mechanisms, reduce by 80% the level of PLK1 mRNA in metastatic breast cancer cells of mouse lungs, and increase the overall survival of treated animals." (PMID 40943628, 2025). "Increasing the activity of PLK1 promotes tumor EMT process and enhances cancer cell invasiveness by interacting with the MEK1/2-ERK1/2-ZEB1/2, FoxM1, and cRAF signaling pathways." (PMID 41458961, 2025). "For instance, in the comparison between PCa tumor and normal samples, DiCE identified 61 cancer fitness genes, including MYC, CCNA2, PLK1, PTTG1, EPCAM, and MTOR, that were overlooked by typical DEA but are well-documented contributors to PCa progression." (PMID 40626556, 2025). "Polo‐like kinase 1 (PLK1) mRNA is modified by m6A and stabilized by binding to IGF2BP2, which increases PLK1 expression and contributes to cancer progression." (PMID 40448344, 2025).